RIPK1 (receptor interacting serine/threonine kinase 1)
Diseases named in the same sentence as RIPK1 in open-access papers (continued):
Sharing a sentence is not in itself a finding about the gene and the disease.
cognitive decline (8 papers, 2021 to 2026). "Preclinical studies have shown that inhibiting RIPK1 genetically or pharmacologically in preclinical models decreased the extent of neurodegeneration and the rate of cognitive decline." (PMID 42193479, 2026). "The authors suggest that progressive chronic brain damage and cognitive decline after TBI depend on RIPK1/3 expression in neurons." (PMID 35054920, 2022). "The data of the current study suggest that progressive chronic brain damage and cognitive decline after TBI depend on the expression of RIPK1/3 in neurons." (PMID 34404478, 2021). "It has been shown that anaesthesia and surgery induce microglial activation, leading to the synthesis and release of inflammatory cytokines and cognitive decline, and that inhibiting the kinase activity of RIPK1 is effective in attenuating microglia and alleviating cognitive decline." (PMID 37329446, 2023). "From our point of view, the combined inhibition of several kinases belonging to a well-described signaling pathway such as the PKR/p38/RIPK1 pathway could bring about a way to target several key points in the detrimental cascade leading to neurodegeneration, neuroinflammation, and cognitive decline." (PMID 33808629, 2021). "Interventions inhibiting key necroptosis molecules such as RIPK1, RIPK3, and MLKL may hold promise for mitigating AD-related pathology and cognitive decline." (PMID 40161268, 2025). "Nec-1s is extensively used in preclinical studies, and several other RIPK1 inhibitors (e.g., DNL474, DNL758) are currently in clinical trials for neurodegenerative diseases suggesting the translational potential of these inhibitors for age-related neuroinflammation and cognitive decline." (PMID 34515928, 2021).
diabetes (8 papers, 2022 to 2025). "For instance, RIPK1 gene variants were associated with diabetes in humans and its down-regulation ameliorated obesity-driven metabolic syndrome." (PMID 40961178, 2025). "It has been reported that the combined administration of insulin and NAC showed myocardial protection for canines with diabetes by promoting the linear ubiquitination of receptor-interacting protein kinase 1 (RIPK1) and NF-κB-essential modulator (NEMO)." (PMID 39339978, 2024). "In addition, we show that the RIPK1‐dependent NLRP3 inflammasome is activated in microglia during diabetes." (PMID 37665158, 2024). "It remains unclear whether RIPK1 regulatory mechanisms are involved in mediating neuroinflammation in diabetes." (PMID 37665158, 2024). "While it is increasingly acknowledged that diabetes is an autoinflammatory condition and its complications stem from a prolonged low-grade inflammatory state, the development of drugs targeting RIPK1 and RIPK3 to alleviate diabetic complications remains inadequate." (PMID 37954576, 2023). "Inhibition of RIPK1 and RIPK3 affects the developmental progression of retinopathy in animal models of diabetes." (PMID 37954576, 2023). "Our findings suggest that the RIPK1/PIP3K pathway mediates cardiotoxic effects of HGF by impairing the autophagic flux, and is a promising therapeutic target in diabetes mellitus induced MF." (PMID 35165268, 2022). "There has been increasing interest in targeting significant regulators of the inflammatory pathway, notably receptor-interacting serine/threonine-kinase-1 (RIPK1) and receptor-interacting serine/threonine-kinase-3 (RIPK3), as drug targets for managing inflammation in treating diabetes complications." (PMID 37954576, 2023). "Thus, the combination of low-dose RIPK1 and RIPK3 inhibitors is an effective strategy against diabetes mellitus induced MF." (PMID 35165268, 2022). "Therefore, a combination of inhibitors targeting RIPK1 and RIPK3 and hypoglycemic drugs may increase effectiveness in treating diabetes mellitus." (PMID 37954576, 2023). "Since overactivation of RIPK1 and RIPK3 can lead to harmful inflammatory responses and tissue damage, understanding the precise mechanisms of RIPK1 and RIPK3 regulation of inflammation and the development of selective inhibitors are of utmost importance for the treatment of diabetes complications." (PMID 37954576, 2023). "In our study, RIPK1, RIPK3, and their phosphorylated forms were up-regulated in HGF-treated CFs and the myocardial tissues of diabetic rats, and inhibition of this pathway abrogated the pathological effects of HGF, suggesting the involvement of necroptosis in diabetes mellitus induced MF." (PMID 35165268, 2022).
gastric cancer (8 papers, 2016 to 2026). A primary or metastatic malignant neoplasm involving the stomach. "RIPK1 Over-expression prevents SHK-induced cell death in gastric cancer cells, whereas RIPK1 knockdown contributes to it." (PMID 27905569, 2016). "Astaxanthin treatment could induce the activation of NADPH oxidase and the activation of RIPK1 medicated necroptosis in a gastric cancer cell line named AGS." (PMID 37588664, 2023). "Notably, Nec-1, an RIPK1 inhibitor, rescued the chelerythrine-induced rapid cell death, indicating that chelerythrine triggers necroptosis in gastric cancer cells." (PMID 37836684, 2023). "Collectively, NME2 was critical for the maintenance of stemness of gastric cancer stem-like cells via promoting the expression of stemness-associated transcriptional factors (c-Myc, LGR5, ALDH1, and Nanog) and anti-apoptosis genes (RIPK1, STARD5, and LIMS1)." (PMID 34628473, 2021). "H19 knockdown promotes resveratrol-induced ER stress and necroptosis of gastric cancer cells by increasing GRP78, receptor-interacting serine/threonine-protein kinase 1 (RIPK1), and mixed lineage kinase domain-like (MLKL) expressions." (PMID 36230902, 2022). "The results of western blot and quantitative real-time PCR showed that the NME2 knockdown significantly downregulated the expression levels of RIPK1, STARD5, and LIMS1 in gastric cancer stem-like cells from human solid tumors." (PMID 34628473, 2021). "In conclusion, SHK does not induce necroptosis in gastric cancer cells, and the expression of RIPK1 has a protective role in SHK-induced apoptosis." (PMID 27905569, 2016).
injury (8 papers, 2021 to 2025). Damage inflicted on the body as the direct or indirect result of an external force, with or without disruption of structural continuity. "Targeting of the key necroptosis regulator RIPK1 or TLR4, which is known to be an inducer of the necroptosis pathway upstream of RIPK1, protects against hyperammonemia-induced liver injury and reduces circulating ammonia levels." (PMID 40053595, 2025). "Our study demonstrates that circCacna1c can improve cardiac function following MI-induced heart injury by inhibiting the Hnrnpf/RIPK1-mediated cardiomyocyte necroptosis." (PMID 39533214, 2024). "Taken together, these findings suggest that inhibiting RIPK1 activity has the potential to ameliorate tissue damage and reduce the inflammatory response in mice with acute lung injury." (PMID 38521771, 2024). "Furthermore, immunochemical staining of RIPK1, RIPK3, and MLKL showed that YQJOF reduces hepatocytic RIPK1, RIPK3, and MLKL levels, which were upregulated in chronic liver injury, acute liver injury, and ACLF model." (PMID 33967802, 2021). "Interestingly, however, the FDA-approved ATP-competitive BRAF inhibitor dabrafenib also inhibits human and mouse RIPK3 without cross-inhibition of RIPK1 and without adverse induction of RIPK1-dependent apoptosis and protects mice from acetaminophen-induced liver injury." (PMID 37409125, 2023).
liver cancer (8 papers, 2019 to 2023). An epithelial or non-epithelial malignant neoplasm that arises from the liver. "AKT activation suppresses RIPK1 inhibitor-induced antiproliferation of liver cancer cells, suggesting that RIPK1 acts as an upstream activator to up-regulate AKT expression." (PMID 36139919, 2022). "The most highly mutated genes, such as MYC, TERT, FASLG, RIPK1, TNFSF10, TARDBP, and CDKN2A, have been well characterized in liver cancer, diffuse large B-cell lymphoma, neuroblastoma, and kidney renal clear cell carcinoma." (PMID 35875102, 2022). "HIF1α/HSP90α and RIPK1 were almost highly expressed in liver cancer tissues." (PMID 33440739, 2021). "Recently, RIPK1 has been proved to have anti-cancer effects, especially preventing proteasome degradation of TRAF2 to control the development of human liver cancer." (PMID 32368189, 2020). "Moreover, knockdown of HABON increased RIPK1 and MLKL expression as well as their phosphorylation level in SMMC-7721 and Huh7 liver cancer cells." (PMID 35387966, 2022). "It looks like RIPK1 has a short survival when highly expressed and the expression of RIPK3 has no obvious effect on the survival of liver cancer." (PMID 33440739, 2021).
Lymphadenopathy (8 papers, 2019 to 2025). Enlargement (swelling) of a lymph node. "As expected, Ripk1K376R/K376RCasp8−/−Ripk3−/− and Ripk1+/+Casp8−/−Ripk3−/− mice developed the lymphadenopathy that is associated with caspase-8 deficiency and therefore were not aged beyond 11–13 weeks." (PMID 32999468, 2021). "In contrast, dominantly-inherited, heterozygous missense mutations in RIPK1 generate a protein which resists caspase cleavage, promoting its ongoing activation and leading to recurrent fevers and lymphadenopathy – a condition known as cleavage-resistant RIPK1-Induced autoinflammatory disease (CRIA)." (PMID 39762600, 2025). "Since RIPK3 and Caspase8 double deficient mice suffer from lymphadenopathy and splenomegaly at an old age41,42, we compared Ripk1+/+, Ripk1Y383F/Y383F, Ripk3−/−Caspase8−/− and Ripk1Y383F/Y383FRipk3−/−Caspase8−/− mice side by side at a young age at 8 weeks and old age at 16 weeks." (PMID 36329033, 2022). "For instance, rare mutations in RIPK1, such as D324N, D324H, and D324Y at the Caspase-8 recognition site LQLD, block Caspase-8-mediated cleavage of RIPK1, resulting in an autosomal-dominant autoinflammatory disease, characterized by recurrent fevers and lymphadenopathy." (PMID 39062098, 2024). "Recently published studies revealed that human non-cleavable RIPK1 variants promoted activation of RIPK1, and led to an increased inflammatory response in PBMCs, which resulted in an early-onset periodic fever syndrome and severe intermittent lymphadenopathy." (PMID 33329521, 2020). "While reducing apoptosis in the intestine, the rescue through haplosufficiency of TRADD did not lead to lymphadenopathy and splenomegaly in the resulting Ripk1−/−Ripk3−/−Tradd+/− mice, unlike the severe lpr-like symptom in Ripk3−/−Fadd−/− or Ripk1−/−Ripk3−/−Fadd−/− mice 29,33." (PMID 30741936, 2019).
steatosis (8 papers, 2021 to 2024). Increased lipid within the cytoplasm of cells. "However, in CD-HFD-fed UGDH-deficient mice, suppression of RIPK1 kinase was unable to reduce hepatic steatosis and inflammation." (PMID 37169760, 2023). "Taken together, these data indicate that pharmacological targeting RIPK1 holds promise for the reducing multiple hallmarks of metabolic liver disease including steatosis, inflammation, and fibrosis." (PMID 38195700, 2024). "They revealed that RIPA-56 inhibits RIPK1 to decrease liver damage, inflammation, fibrosis, and steatosis in animal models in either a curative or preventative manner." (PMID 37910384, 2023). "Taken together, these results suggest that the deSUMOylation activity of SENP1 is important in suppressing RIPK1 activation, and subsequent apoptosis, inflammation, and steatosis." (PMID 36414671, 2022). "RIPK1 inhibition by RIPA‐56 reversed steatosis irritated by HFD, as evidenced by reduced hepatic triglyceride (TG) content." (PMID 35083817, 2022). "In our study, we confirm the existence of necroptosis in our in vitro hepatocyte steatosis and hypoxia model as evidenced by alterations in the expression of RIPK1, RIPK3 and MLKL." (PMID 33435617, 2021). "The absence of RIPK3 attenuated cell death, steatosis and mitochondrial ROS production, and RIPK1 deficiency dampened hepatic inflammation after alcohol exposure." (PMID 35083817, 2022). "Therefore, we believe that RIPK3 accumulation following alcohol exposure contributes to cell death and steatosis, and RIPK1 activity is required for alcohol‐induced hepatic inflammation." (PMID 35083817, 2022). "Interestingly, inhibition of RIPK1 in Senp1f/f;Alb-Cre;Ripk1D138N/D138N mice strongly suppressed steatosis." (PMID 36414671, 2022). "In line with this study, Majdi and colleagues showed that the inhibition of RIPK1 improved NASH characteristics in HFD-fed mice and reversed steatosis through an MLKL-dependent mechanism that mainly affects mitochondrial respiration." (PMID 37910384, 2023). "In addition, in patients with NASH, serum concentrations of RIPK1 and MLKL increase with activity, and RIPK1 inhibition improves NASH features in high-fat diet-fed mice and reverses steatosis via an MLKL-dependent mechanism." (PMID 36110858, 2022). "However, inhibiting the kinase activity of RIPK1, which normally activate RIP3, only attenuates alcohol-induced hepatic inflammation but does not offer protection against steatosis and liver injury resulting from chronic ethanol consumption." (PMID 38195700, 2024). "Inactivating RIPK1 in Ugdhf/f;Alb-Cre;Ripk1D138N/D138N mice did not affect body weight and liver weight after feeding CD-HFD, nor did it affect hepatic steatosis and lipid accumulation as determined by H&E and ORO staining, as well as hepatic TG, TC and NEFA measurement." (PMID 37169760, 2023).
Hepatitis (7 papers, 2016 to 2022). Inflammation of the liver. "This work underlines the interest to focus studies on RIPK1 in other hepatitis models, and especially in acetaminophen (APAP) liver toxicity, where the role attributed to RIPK1 is not yet fully understood." (PMID 27831558, 2016). "In conclusion, our results underline the protective role of RIPK1 in dysimmune hepatitis and the risks of potential defects in the RIPK1 scaffolding function that would sensitize hepatocyte to the death, risking to worsen hepatitis and even to the increase of HCC onset." (PMID 27831558, 2016). "Indeed, inactivation of RIPK1 activity either by Nec-1S or genetic modification greatly protected ConA-challenged mice from hepatitis, demonstrating a key role of RIPK1 kinase activity in ConA-induced hepatocyte death." (PMID 27831558, 2016). "These later observations meant that in acute CCl4-induced hepatitis, TNF-α would help protect hepatocytes through both RIPK1-independent and dependent mechanisms." (PMID 35806372, 2022). "Further, pharmacological inhibition of RIPK1 by Nec1s also had no impact on CCl4-induced hepatitis in mice." (PMID 35806372, 2022). "We took advantage of two different deficient mouse lines, the RIPK1 kinase dead knock-in mice (Ripk1K45A) and the conditional knockout mice lacking RIPK1 only in liver parenchymal cells (Ripk1LPC-KO), to characterize the role of RIPK1 and TNF-α in hepatitis induced by concanavalin A (ConA)." (PMID 27831558, 2016). "Thus, to characterize the role of RIPK1 in hepatitis, we took advantage of two genetically modified mouse lines, the RIPK1 kinase dead knock-in mice (Ripk1K45A) and the conditional knockout mice lacking RIPK1 only in liver parenchymal cells (Ripk1LPC-KO)." (PMID 27831558, 2016).
leukemia (7 papers, 2018 to 2025). A malignant (clonal) hematologic disorder, involving hematopoietic stem cells and characterized by the presence of primitive or atypical myeloid or lymphoid cells in the bone marrow and the blood. "It has been used to treat leukemia in previous studies and was later classified as an unclassified RIPK1 inhibitor after its inhibitory effect on RIPK1 was found." (PMID 36993980, 2023). "Moreover, triggering a RIPK1-mediated apoptotic and/or necroptotic death by smac mimetics against leukemia seems promising." (PMID 30158588, 2018). "Necroptosis inhibitor necrostatin-1 targeting RIPK1 or siRNA-mediated knockdown of RIPK1 significantly enhanced SHK-induced apoptosis in K562, HL-60, and primary leukemia cells." (PMID 38026987, 2023). "Staurosporine has been reported to induce RIPK1 and MLKL-dependent necroptotic cell death in leukemia cells when caspase activation is compromised." (PMID 36199434, 2022). "Recently, Staurosporine has been found to trigger RIPK1- and MLKL-dependent necroptosis in leukemia under caspase-compromised conditions." (PMID 33665167, 2020).